TIPE1 (TNF alpha induced protein 8 like 1)
Diseases named in the same sentence as TIPE1 in open-access papers (continued):
Sharing a sentence is not in itself a finding about the gene and the disease.
osteosarcoma (4 papers, 2019 to 2023). A usually aggressive malignant bone-forming mesenchymal neoplasm, predominantly affecting adolescents and young adults. "We thus postulated that TIPE1 inhibits the tumorigenesis and progression of osteosarcoma by regulating PRMT1-mediated STAT3 expression." (PMID 36151091, 2022). "A previous study suggested that TIPE1 suppresses osteosarcoma cancer cell growth by inhibiting MCP-1 expression in osteosarcoma cells, thus inhibiting the MCP-1/CCR2 axis via macrophage-osteosarcoma cell crosstalk." (PMID 36151091, 2022). "We further investigated endogenous TIPE1 expression levels in osteosarcoma cell lines by using western blotting and qPCR methods." (PMID 36151091, 2022). "Functional assays showed that TIPE1 inhibited osteosarcoma carcinogenesis and metastatic potential both in vivo and in vitro." (PMID 36151091, 2022). "The expression of TIPE1 was significantly lower in metastatic osteosarcoma samples than in primary osteosarcoma samples." (PMID 36151091, 2022). "Our data showed that TIPE1 inhibits osteosarcoma occurrence and metastasis both in vivo and in vitro." (PMID 36151091, 2022). "We reported that TIPE1 inhibited cell proliferation, migration and invasion in the carcinogenesis of osteosarcoma by inhibiting PRMT1-mediated STAT3 function." (PMID 36151091, 2022). "Next, CCK-8, colony formation and cell cycle assays were performed to further substantiate the role of TIPE1 in osteosarcoma progression." (PMID 36151091, 2022). "The CCK-8 results showed that overexpression of TIPE1 decreased the proliferation rate of MNNG/HOS Cl #5 cells compared to the controls, indicating that TIPE1 inhibited the proliferation of osteosarcoma cells." (PMID 36151091, 2022). "In this study, we showed that TIPE1 could suppress the development and progression of osteosarcoma both in vivo and in vitro." (PMID 36151091, 2022). "TIPE1 might be a potential molecular therapeutic target and an early biomarker for osteosarcoma diagnosis." (PMID 36151091, 2022). "Furthermore, the protein expression of TIPE1 was significantly lower in metastatic osteosarcoma samples (clinical stage IV) than in primary osteosarcoma samples (clinical stage I and II)." (PMID 36151091, 2022). "However, it primarily showed that TIPE1 inhibits osteosarcoma progression by suppressing macrophage functions." (PMID 36151091, 2022). "Ki67 staining of the tumor samples was performed to determine the cell proliferation rate, and the results indicated that TIPE1 might have tumor suppression potential in osteosarcoma." (PMID 36151091, 2022). "Similarly, PRMT1 significantly restored the osteosarcoma cell migration rate that was previously suppressed by TIPE1." (PMID 36151091, 2022). "More importantly, we demonstrated that overexpression of PRMT1 rescued TIPE1-caused the inhibition of cell proliferation, and administration of STAT3 inhibitor can abolish this inhibition, indicating that TIPE1 inhibits osteosarcoma proliferation primarily via PRMT1-mediated STAT3 suppression." (PMID 36151091, 2022). "Given that osteosarcoma in the late-stage present with stronger invasive capacity and metastatic potential than osteosarcoma in the earlier stage, TIPE1 might be involved in the progression and vascular invasion of osteosarcoma." (PMID 36151091, 2022). "This study provides a proof of concept that targeting TIPE1 may be a therapeutic strategy for osteosarcoma." (PMID 36151091, 2022). "To determine whether TIPE1 inhibits osteosarcoma tumorigenesis and progression via PRMT1 specifically, we transfected TIPE1 into osteosarcoma cells with or without PRMT1." (PMID 36151091, 2022). "The results from the in vitro and in vivo studies, together with the analysis of patient specimens, collectively showed that TIPE1 could suppress the development and progression of osteosarcoma." (PMID 36151091, 2022).
osteosarcoma (continued). "Moreover, very recent studies indicated that TIPE1 suppresses tumor growth, invasion, and migration in osteosarcoma, lung cancer, and gastric carcinoma." (PMID 31179241, 2019). "Therefore, we investigated how TIPE1 participates in the progression of osteosarcoma." (PMID 36151091, 2022). "Therefore, combined with previous studies, we believe that PRMT1 might be the most likely candidate protein that interacts with TIPE1 to participate in the procession of osteosarcoma." (PMID 36151091, 2022). "Thus, in this context, we asked how TIPE1 participates in the development of osteosarcoma." (PMID 36151091, 2022). "More importantly, our Affymetrix Gene Chip results also demonstrated that the expression of MCP-1(CCL2) was not significantly changed after TIPE1 transfection, demonstrating that there might be other more important mechanisms involved in TIPE1-mediated osteosarcoma tumorigenesis and progression." (PMID 36151091, 2022). "In this study, we showed that TIPE1 inhibits STAT3 transactivation and expression via PRMT1, resulting in decreased osteosarcoma tumorigenesis and progression." (PMID 36151091, 2022). "The results showed that TIPE1 specifically decreased the expression level of total STAT3 and p-STAT3 in osteosarcoma cells, instead of the expression of total Jak2 and p-Jak2." (PMID 36151091, 2022). "We further detected the protein expression of TIPE1 and STAT3 in 20 osteosarcoma tissues by immunohistochemical staining." (PMID 36151091, 2022). "Here, we report that TIPE1 is a novel STAT3 pathway regulator and a tumor suppressor in osteosarcoma." (PMID 36151091, 2022). "Taken together, these data showed that TIPE1 inhibits the malignant transformation of osteosarcoma through PRMT1-mediated STAT3 arginine methylation and ultimately decreases the development and metastasis of osteosarcoma." (PMID 36151091, 2022). "Here, we reported that TIPE1 expression was decreased in osteosarcoma tissues compared to normal and adjacent nontumor tissues, and its expression was negatively related to tumor stage and tumor size." (PMID 36151091, 2022). "How TIPE1 affects the tumorigenesis and progression of osteosarcoma cells has not been clearly demonstrated." (PMID 36151091, 2022). "The results also showed that both the mRNA and protein expression levels of TIPE1 in osteosarcoma tissues were lower than those in adjacent nontumor tissues." (PMID 36151091, 2022). "Gene expression and Ingenuity Pathway Analysis (IPA) analyses demonstrated that the STAT3 pathway was inhibited after transfection of a TIPE1 expression vector, suggesting that TIPE1 could inactivate the STAT3 signaling pathway and inhibit the malignant biological behavior of osteosarcoma." (PMID 36151091, 2022). "Furthermore, we showed that low expression of TIPE1 was related to advanced-stages of osteosarcoma and that the expression of TIPE1 had a negative relationship with the expression of STAT3 in osteosarcoma patients." (PMID 36151091, 2022). "However, due to the missing five-year survival data, we could not analyze the five-year survival of patients with osteosarcoma with respect to TIPE1 expression." (PMID 36151091, 2022).
ovarian carcinoma (3 papers, 2019 to 2022). A malignant neoplasm originating from the surface ovarian epithelium. "Our previous studies suggested that TIPE1 was associated with ovarian cancer metastasis, so we attempted to evaluate the effect of TIPE1 on migration ability in ovarian cancer cells." (PMID 34188681, 2021). "All these data suggested that deficiency of TIPE1 expression was involved in ovarian cancer cells development." (PMID 34188681, 2021). "To further determine the function of TIPE1 on the biological behaviors of ovarian cancer cells, we employed lentivirus-based TIPE1 expressing system to infect ovarian cancer cell lines, and puromycin was added to select the stable expression cells." (PMID 34188681, 2021). "IHC staining level of TIPE1 in these tissues indicated that TIPE1-positive cells were rarely observed among ovarian cancer but obvious in the ovarian stroma." (PMID 34188681, 2021). "Statistical analysis of clinical characteristics of these patients also demonstrated that TIPE1 expression was negatively correlated with metastasis in ovarian cancer." (PMID 34188681, 2021). "More importantly, mean IHC score displayed that protein levels of TIPE1 decreased significantly in ovarian cancer tissues characterized by tumor metastasis." (PMID 34188681, 2021). "In the current study, we proved that TIPE1 was negatively correlated with metastasis and inhibited the migration ability of cells in ovarian cancer." (PMID 34188681, 2021). "In the current study, we aimed to reveal the protein expression spectrum of TIPE1 in normal human tissues and explored its relationship with metastasis in ovarian cancer." (PMID 34188681, 2021). "Therefore, it is necessary to explore the relationship between TIPE1 and metastasis and to further clarify its anti-tumor effect in ovarian cancer." (PMID 34188681, 2021). "Taken together, our results demonstrate the suppressor role of TIPE1 in ovarian cancer metastasis, indicating TIPE1 might be a metastasis predictor and a novel therapeutic target for ovarian cancer." (PMID 34188681, 2021). "A recent study reported that TIPE1 was decreased in tissue microarrays and inhibited proliferation through inducing apoptosis in ovarian cancer cells, but whether TIPE1 related to tumor metastasis was not mentioned." (PMID 34188681, 2021). "Our findings revealed the function of TIPE1 in ovarian cancer and suggested that TIPE1 may be a novel therapeutic target for patients." (PMID 34188681, 2021). "In the current study, we investigated the expression and function of TIPE1 in ovarian cancer." (PMID 34188681, 2021). "Secondly, overexpressed TIPE1 could increase the protein level of E-Cadherin but decrease the protein level of N-Cadherin, Slug, and Snail, indicating that overexpressed TIPE1 could inhibit the epithelial-mesenchymal transition of ovarian cancer cells." (PMID 34188681, 2021). "Moreover, TIPE1 protein was downregulated in ovarian cancer tissues compared with that in the paracancerous." (PMID 34188681, 2021). "TIPE1, which may be involved in immune regulation and tumorigenesis, is known to be downregulated in ovarian cancer tissues, suggesting that TIPE1 may suppress the metastasis and tumorigenesis of ovarian cancer." (PMID 36118167, 2022). "Moreover, overexpressed TIPE1 increased the protein of E-Cadherin but suppressed N-Cadherin, Slug, and Snail expression, which suggested that TIPE1 could inhibit the EMT of ovarian cancer cells." (PMID 34188681, 2021). "It was reported that TIPE1 was decreased in cancer tissues and inhibited ovarian cancer cell growth, but the relationship of TIPE1 and metastasis was not mentioned." (PMID 34188681, 2021). "TIPE1, a newly identified member in TIPE (TNFAIP8) family, plays an important role in tumorigenesis and immune regulation, but its role in ovarian cancer, especially in tumor metastasis, remains unknown." (PMID 34188681, 2021).
ovarian carcinoma (continued). "The expression of TIPE in clinical specimens and pathological data indicated that TIPE1 was a suppressor gene in ovarian cancer and it was negatively correlated with cancer metastasis." (PMID 34188681, 2021). "More importantly, TIPE1 suppressed tumorigenesis and metastasis of ovarian cancer in vitro and in vivo, as evidence shows its ability to suppress growth, colony formation, migration, and epithelial-mesenchymal transition (EMT) of ovarian cancer." (PMID 34188681, 2021). "Furthermore, overexpression of TIPE1 in ES2 and SKOV3 cells decreased the closure of wound area compared to the control, and Transwell assays also confirmed that TIPE1 down-regulated migratory abilities of ovarian cancer cells." (PMID 34188681, 2021). "Besides, we had also analyzed the relationship between TIPE1 expression and patient age, tumor size, histology, differentiation grade, and clinical stage of 281 ovarian cancer patients, but unfortunately, no statistical significance between them was observed." (PMID 34188681, 2021). "To evaluate the role of TIPE1 in the development of ovarian cancer, we used murine xenograft in Balb/c mice with SKOV3 cells with or without TIPE1 overexpression." (PMID 34188681, 2021).
colorectal cancer (2 papers, 2017 to 2020). A primary or metastatic malignant neoplasm that affects the colon or rectum. "TIPE1 can also impair the stemness of colorectal cancer by directly targeting β‐catenin." (PMID 32588529, 2020).
diabetes (2 papers, 2024). "In this study, we found that Tipe1 deficiency in islet β cells led to pre‐diabetes phenotype, including glucose intolerance and impaired insulin secretion under physiological conditions." (PMID 38417114, 2024). "Moreover, Tipe1 knockdown caused severe diabetes phenotypes in obese conditions." (PMID 38417114, 2024). "In the present study, we observed that vitamin D supplementation mitigated the damage to human umbilical vein endothelial cells (HUVECs) induced by type 2 diabetes mellitus, likely through the down-regulation of TIPE1." (PMID 38216955, 2024). "In summary, we found a negative correlation between blood glucose levels and the expression of Tipe1 and Gαs in human islet β cells, further indicating that Tipe1 has a potential therapeutic role as a regulator of Gαs in diabetes mellitus." (PMID 38417114, 2024). "The results show that the β‐cell‐specific knockout of Tipe1 (termed Ins2‐Tipe1BKO) aggravated diabetic phenotypes in db/db mice or in mice with high‐fat diet‐induced diabetes." (PMID 38417114, 2024). "This highlights the potential therapeutic role of Tipe1 in the management of diabetes symptoms." (PMID 38417114, 2024).
diabetic nephropathy (2 papers, 2023 to 2024). "Furthermore, the upregulation of TIPE1 in renal tubular epithelial cells in a high glucose environment disrupted mitophagy and facilitated the advancement of diabetic nephropathy." (PMID 38216955, 2024).
gastric cancer (2 papers, 2018 to 2020). A primary or metastatic malignant neoplasm involving the stomach. "We found that the decreased levels of TIPE1 were associated with degree of gastric cancer cell differentiation by mRNA analysis and immunohistochemical staining." (PMID 28994231, 2018). "Collectively, these findings provide new evidence for a better understanding of the biological activities of TIPE1 in progression and metastasis of gastric cancer and suggest that TIPE1 may be an innovative diagnostic and therapeutic target of gastric cancer." (PMID 28994231, 2018). "TIPE1 is also present in many cancer cells of epithelial origin, including breast, cervical, bladder and gastric cancer cells." (PMID 32588529, 2020). "In this study, we found that the levels of TIPE1 were significantly reduced and inversely correlated with differentiation status and distant metastasis in primary gastric cancer tissues." (PMID 28994231, 2018). "In the present study, we found that the levels of TIPE1 were significantly reduced and were inversely correlated with differentiation status and distant metastasis in patients with primary gastric cancer." (PMID 28994231, 2018). "Consistently, gene silencing of TIPE1 in well‐differentiated gastric cancer cell line (AGS) inhibited these processes." (PMID 28994231, 2018). "Our results showed that the levels of TIPE1 were lower in low‐differentiated gastric cancer cell lines including SGC7901, BGC823 and MKN45 than those of well‐differentiated AGS cell lines." (PMID 28994231, 2018). "Taken together, our data strongly support that TIPE1 is a potential suppressor of EMT in gastric cancer." (PMID 28994231, 2018). "This study was designed to investigate the potential role of TIPE1 in gastric cancer invasion, progression and metastasis." (PMID 28994231, 2018). "The reduction of TIPE1 in poorly cohesive gastric carcinoma tissues was also confirmed by immunofluorescence staining and Western blot." (PMID 28994231, 2018). "Gelatin zymography assay further indicated the activity of MMP2 and MMP9 was restrained by TIPE1 in BGC823 cells, which may partially explain that TIPE1 can inhibit migratory and invasive behaviours in gastric cancer cells." (PMID 28994231, 2018). "This study for the first time demonstrates that TIPE1 plays a functional role in metastasis, suggesting that TIPE1 may serve as a potential therapeutic target for advanced gastric cancer." (PMID 28994231, 2018). "To study whether TIPE1 is associated with degree of tumour cell differentiation, we surveyed the expression levels of TIPE1 in a panel of gastric cancer cell lines that are derived from tumours with various degrees of differentiation." (PMID 28994231, 2018). "Furthermore, we found that TIPE1 negatively regulated cell invasion and metastasis capacities in gastric cancer cells." (PMID 28994231, 2018). "Collectively, we found that TIPE1 inhibits gastric cancer invasion and migration, suggesting that TIPE1 may be an innovative therapeutic strategy for treating patients with gastric cancer." (PMID 28994231, 2018). "In this study, we further explored the role of TIPE1 in the development of gastric carcinoma." (PMID 28994231, 2018). "However, we found that TIPE1 could suppress the migration and invasion of gastric cancer through inhibiting EMT." (PMID 28994231, 2018). "We further analysed the expression of TIPE1 from 102 cases of primary gastric cancer specimen stratified by TNM stage, distant metastasis, tumour location and degree of gastric cancer cell differentiation." (PMID 28994231, 2018). "However, whether TIPE1 is involved in gastric cancer progression and metastasis keeps unknown." (PMID 28994231, 2018). "In this study, we found that TIPE1 inhibits EMT as demonstrated by the significant up‐regulation of E‐cadherin expression and downregulation of vimentin and transcription factors in gastric cancer cells." (PMID 28994231, 2018).
gastric cancer (continued). "By Agilent Whole Human Genome Oligo Microarray for global human gene expression analysis, we found that among TIPE family, the levels of TIPE1 and TIPE3 were decreased in poorly cohesive gastric carcinoma tissues compared with adjacent non‐tumour tissues." (PMID 28994231, 2018). "We further observed overexpression of TIPE1 in aggressive gastric cancer cell lines decreased their metastatic properties both in vitro and in vivo as demonstrated by markedly inhibiting EMT and metastasis of gastric cancer cells in nude mice." (PMID 28994231, 2018). "However, the expression of TIPE1 was inversely correlated with differentiation status (P = 0.001), aggregated degree (P = 0.030), lymph node status (P = 0.040), distant metastasis (P = 0.003) and TNM stage (P = 0.022) of patients with gastric cancer." (PMID 28994231, 2018).
sarcoma (2 papers, 2018 to 2022). A usually aggressive malignant neoplasm of the soft tissue or bone. "First, we used the GEPIA website to determine the TIPE1 expression levels in sarcoma (SARC) tissues and normal tissues." (PMID 36151091, 2022). "The results showed that the levels of TIPE1 in sarcoma tissues were significantly lower than those in normal tissues." (PMID 36151091, 2022).